CTCF (CCCTC-binding factor)
Diseases named in the same sentence as CTCF in open-access papers (continued):
Sharing a sentence is not in itself a finding about the gene and the disease.
squamous cell carcinoma (2 papers, 2015 to 2023). A carcinoma arising from squamous epithelial cells. "This position also overlapped with the strongest CTCF ChIP-seq signal observed in the uterine squamous cell carcinoma cell line SiHa." (PMID 37365652, 2023). "We propose the hypothesis that increased methylation at the CpG islands might interfere with the binding of the CTCF repressor with the c-KIT promoter which regulates c-KIT proto-oncogene expression in c-KIT (+) squamous cell carcinoma of uterine cervix." (PMID 26607501, 2015).
acute promyelocytic leukemia (1 paper, 2021). An aggressive form of acute myeloid leukemia (AML), characterized by arrest of leukocyte differentiation at the promyelocyte stage, due to a specific chromosomal translocation t(15;17) in myeloid cells. "The overexpression of Dlk1-Dio3 miRNAs in acute promyelocytic leukemia (APL) has been associated with the hypermethylation of conserved binding sites for the CCCTC-binding factor (CTCF, an enhancer blocking protein) at MEG3-DMR." (PMID 34062726, 2021).
adrenocortical carcinomas (1 paper, 2022). "Interestingly, adrenocortical carcinomas and testicular germ cell cancers frequently feature amplifications of the CTCF coding sequence, which might lead to CTCF overexpression." (PMID 35993175, 2022).
amyotrophic lateral sclerosis (1 paper, 2013). Amyotrophic lateral sclerosis (ALS) is a neurodegenerative disease characterized by progressive muscular paralysis reflecting degeneration of motor neurons in the primary motor cortex, corticospinal tracts, brainstem and spinal cord. "For instance, an LTR12C repeat, comprising part of the long noncoding RNA BC041449 that is located directly upstream of the amyotrophic lateral sclerosis gene SOD1, is occupied by CTCF in Tc1-mouse liver, but not in human." (PMID 23246434, 2013).
Ataxia (1 paper, 2022). Ataxia refers to impaired coordination of voluntary muscle movement. "Approximately 3 weeks after birth, CTCF-cKO mice, represented by the genotype Ctcf;Grid2-Cre (fl/fl; +/Cre), showed obvious differences in appearance with growth retardation and ataxia-like motor abnormalities as compared with mice of other genotypes." (PMID 36447271, 2022).
autosomal dominant intellectual disability (1 paper, 2023). "In conclusion, our study demonstrates that autosomal dominant intellectual disability can be caused by exon deletion (c.1519_2184del) and inframe deletion variants (c.1838_1852del) in the CTCF gene." (PMID 37664546, 2023).
bacterial pneumonia (1 paper, 2024). Acute infection of the lung parenchyma caused by bacteria (e.g., Streptococcus pneumoniae, Haemophilus influenzae, Chlamydia pneumoniae, Mycoplasma pneumoniae, and Legionella pneumophila). "Furthermore, the revealed mechanism of the METTL3/NEAT1/CTCF/MUC19 axis provides new theoretical knowledge for bacterial pneumonia treatment and furnishes evidence for future therapeutic direction." (PMID 38757482, 2024).
brain cancer (1 paper, 2016). A primary or metastatic malignant neoplasm affecting the brain. "Another naturally-occurring example of this was recently shown in the context of brain cancer, where hypermethylation at particular CTCF sites in low-grade IDH1-mutant gliomas leads to differential CTCF binding, changes in genome topology, and consequent dysregulation of proto-oncogenes." (PMID 26876719, 2016).
childhood onset asthma (1 paper, 2023). Asthma that starts in childhood. "Allele-specific chromatin remodeling mediated by CTCF was linked to differential expression of genes in the 17q12-q21 locus, which has been linked to childhood-onset asthma." (PMID 38168374, 2023).
chronic kidney disease (1 paper, 2021). Impairment of the renal function secondary to chronic kidney damage persisting for three or more months. "It is reported that CTCF can regulate miR-185-5p/NPHS2 axis with a net effect of alleviating renal interstitial fibrosis in chronic kidney disease." (PMID 34424825, 2021).
clear cell carcinoma (1 paper, 2017). "Among the 8 tumours that relapsed, 3 showed CTCF deletion including a grade 2 endometrioid tumour and two clear cell carcinomas." (PMID 28319062, 2017).
congenital cardiomyopathy (1 paper, 2025). "Clinical studies have associated CTCF mutations with congenital developmental abnormalities, including congenital cardiomyopathy." (PMID 39682078, 2025).
Cri-du-chat syndrome (1 paper, 2022). Monosomy 5p, also known as Cri du chat syndrome, is a rare autosomal deletion syndrome characterized by a mewing cry (cri du chat) in infancy, multiple congenital anomalies, intellectual disability, microcephaly, and facial dysmorphism. "BRD9 has in fact been shown to regulate EZH2 expression by binding together with CTCF in an EZH2 enhancer, but we do not know if EZH2 expression changes contribute to Cri du chat syndrome pathogenesis." (PMID 36242045, 2022).
cystic fibrosis (1 paper, 2016). Autosomal recessive disorder caused by pathogenic variants in the CFTR gene (cystic fibrosis transmembrane conductance regulator), which encodes a chloride and bicarbonate channel expressed in epithelial cells, and follow the diagnosis criteria. "One of the earliest successful applications of CRISPR in stem cell research was to correct the CTCF mutation in cultured intestinal stem cells from cystic fibrosis patients." (PMID 26880991, 2016).
dentatorubral-pallidoluysian atrophy (1 paper, 2008). Dentatorubral pallidoluysian atrophy (DRPLA) is a rare subtype of type I autosomal dominant cerebellar ataxia (ADCA type I). "In the case of SCA7 and a number of other highly unstable CAG/CTG repeat loci, including HD, DM1, SCA2, and dentatorubral-pallidoluysian atrophy, binding sites for a protein known as CTCF (i.e. the “CCCTC binding factor”) have been found." (PMID 19008940, 2008).
ductal carcinomas (1 paper, 2004). "Since CTCF targets include TSGs and oncogenes and it has the ability to inhibit cell growth and proliferation, it has been suggested that it may be the target gene at the 16q22.1 in ductal carcinomas." (PMID 15354217, 2004).
embryonal carcinoma (1 paper, 2014). A non-seminomatous malignant germ cell tumor characterized by the presence of large germ cells with abundant cytoplasm resembling epithelial cells, geographic necrosis, high mitotic activity, and pseudoglandular and pseudopapillary structures formation. "It is possible that a functional relationship between RBPJ and CTCF is restricted to developmentally early cells, represented by the F9 embryonal carcinoma cell line, in which both CTCF and RBPJ play prominent roles." (PMID 24603501, 2014).
Encephalocele (1 paper, 2024). A neural tube defect characterized by sac-like protrusions of the brain and the membranes that cover it through openings in the skull. "As a positive control, we also re-targeted the CTCF cluster C1-C4 which, as expected, resulted in encephalocele in embryos carrying the C1-C4Δ allele." (PMID 39372737, 2024).
endometrioid tumor (1 paper, 2016). A benign, borderline, or malignant epithelial tumor of the female reproductive system characterized by the presence of glands and/or cysts lined by neoplastic cells that resemble endometrial cells. "A recent study concerning the expression of BORIS and its paralog CTCF in EMCAR showed that BORIS RNA was significantly increased in non-endometrioid tumors compared with endometrioid tumors." (PMID 27618037, 2016).
fatty liver (1 paper, 2021). "A previous study in liver diseases showed that CTCF combines with maternal hypomethylation imprinting control region (ICR) to promote the expression of lncRNA H19, which is a regulator of fatty liver, fibrosis, and other liver diseases, suggesting that CTCF may play a role in NAFLD." (PMID 34566670, 2021).
glaucoma (1 paper, 2017). Increased pressure in the eyeball due to obstruction of the outflow of aqueous humor. "α-1B glycoprotein, the transcriptional repressor CTCF, and the neurofilament light polypeptide, which MS revealed were also altered, but which were not included in the displayed protein network, have previously been reported to be associated with glaucoma." (PMID 29135941, 2017).
histiocytic lymphoma (1 paper, 2009). "It is noteworthy that more than 67% of CTCF binding sites occupied by proteins in IMR90 cells were also found to be occupied in human histiocytic lymphoma U937 cells, suggesting constitutive binding of CTCF to a majority of its sites." (PMID 20119526, 2009).
Huntington disease (1 paper, 2021). Huntington disease (HD) is a rare neurodegenerative disorder of the central nervous system characterized by unwanted choreatic movements, behavioral and psychiatric disturbances and dementia. "For instance, CTCF may play a role in regulating Huntington’s (HTT) promoter function in Huntington’s disease." (PMID 34720873, 2021).
Hyperglycemia (1 paper, 2023). An increased concentration of glucose in the blood. "Indeed, hyperglycemia further reduced MTOR methylation in diabetic HAECs and associated with enriched CTCF and Pol2B binding on the MTOR gene." (PMID 36633903, 2023).
hypothyroidism (1 paper, 2023). Abnormally low levels of thyroid hormone. "Another SNP rs4409785 has the largest fold change on CTCF and CTCF-cohesin and a larger b score in self-reported hypothyroidism/myxoedema and RA, and levothyroxine sodium and RA." (PMID 37324262, 2023).
influenza (1 paper, 2024). An acute viral infection of the respiratory tract, occurring in isolated cases, in epidemics, or in pandemics; it is caused by serologically different strains of viruses (influenzaviruses) designated A, B, and C, has a 3-day incubation period, and usually lasts for 3 to 10 days. "In addition, it has been shown that read-through transcription by RNAPII following in vitro infection of monocytes with influenza can displace cohesin from CTCF sites proximal to the TTS, thereby eliminating specific CTCF-anchored loops." (PMID 38636335, 2024).
insomnia (1 paper, 2011). A sleep disorder characterized by difficulty in falling asleep and/or remaining asleep. "Hence, dysregulation of ROR1, PLCB1, or PLCB4 by PAX6 and CTCF may be one mechanism that links neural and pancreatic dysfunction not only in insomnia but also in the relevant psychiatric disorders that are accompanied with circadian rhythm disruption and metabolic syndrome." (PMID 21494683, 2011).
Insulin resistance (1 paper, 2018). Increased resistance towards insulin, that is, diminished effectiveness of insulin in reducing blood glucose levels. "We detected transcription factors CTCF, CTCFL, and Egr1 binding to the genomic region overlapping the differentially methylated CpG within EML3 gene; out of these, CTCF is proved to mediate glucagon production and Egr1 is responsible for insulin resistance." (PMID 30545422, 2018).
kidney cancer (1 paper, 2019). Primary or metastatic malignant neoplasm involving the kidney. "ARNT, CTCF, POLR2A, RAD21 and REST were downregulated in kidney cancer samples and indicated poor prognosis when lowly expressed, which revealed that ARNT, CTCF, POLR2A, RAD21 and REST tended to be risk factors with lower gene expression." (PMID 31727869, 2019).
male infertility (1 paper, 2021). The inability of the male to effect fertilization of an ovum after a specified period of unprotected intercourse. "None of these major contributors to male infertility were prominent in CTCF HET or BORIS KO mice." (PMID 34158481, 2021).
metabolic dysfunction-associated steatohepatitis (1 paper, 2025). Metabolic dysfunction-associated steatohepatitis (MASH, formerly known as nonalcoholic steatohepatitis or NASH) is a type of fatty liver disease. "It has been shown that DDX17 is elevated and transcriptionally represses Cyp2c29 gene expression by cooperating with CCCTC binding factor (CTCF) and DDX5 in the murine model of metabolic dysfunction associated steatohepatitis (MASH) induced by HFD." (PMID 40136664, 2025).
metastatic cancer (1 paper, 2021). A carcinoma which has spread from the original site of growth to another anatomic site. "Similar to the overall trends of contact domains and contact domain boundaries, the number of loops also increased dramatically in metastatic cancer cells, and the proportion of CTCF-mediated chromatin loops was also significantly decreased in metastatic cancer cells." (PMID 34348759, 2021).
metastatic melanoma (1 paper, 2012). A melanoma that has spread from its primary site to another anatomic site. "Therefore, the expression pattern of human NDRG2, VDR, NSD1, CTCF and SRC genes in several human metastatic melanoma cell lines in comparison to primary melanocytes were analyzed at mRNA level by RT-qPCR methodology." (PMID 22984562, 2012).
monocytic leukemia (1 paper, 2014). "When applied for CTCF in K562 human monocytic leukemia cells, it indicated 120,000 intra-chromosomal, CTCF-mediated chromatin interactions representing differently sized chromatin domains." (PMID 24763502, 2014).
myelodysplastic syndrome (1 paper, 2025). A clonal hematopoietic disorder characterized by dysplasia and ineffective hematopoiesis in one or more of the hematopoietic cell lines. "SF3B1 mutations, which are prevalent in myelodysplastic syndrome (MDS) and leukemia, result in missplicing of Brd9 and a subsequent loss of ncBAF at CTCF-associated loci." (PMID 40523422, 2025).
myeloid neoplasm (1 paper, 2025). Proliferation of myeloid cells originating from a primitive stem cell. "Of the 17 patients with reversions or telomere maintenance variants, only the 2 with CTCF variants (ages 58 and 70) had a myeloid neoplasm at the time of evaluation." (PMID 40179146, 2025).
myocardial infarction (1 paper, 2023). Gross necrosis of the myocardium, as a result of interruption of the blood supply to the area, as in coronary thrombosis. "Mechanically, HLA complex P5 (HCP5) and myocardial infarction associated transcript (MIAT), upregulated the expression of PD-L1/CD274 by sponging miR-150-5p, which is regulated by the transcriptional axis of lip-polysaccharides (LPS) -CCCTC binding factor (CTCF)." (PMID 36810034, 2023).
myotonic dystrophy (1 paper, 2009). An inherited progressive disorder affecting the muscles. "CTCF is displaced in the presence of very large expansions of a nearby CTG triplet-repeat sequence, resulting in spreading of antisense transcription and heterochromatin formation beyond their limited confines, leading to congenital myotonic dystrophy." (PMID 19956589, 2009).
neuropathies (1 paper, 2020). "Thus, manipulating CTCF function and activity in SCs may provide a therapeutic means of reversing adverse neuropathies." (PMID 32807777, 2020).
oesophageal cancer (1 paper, 2021). "For example, oesophageal cancer showed a strong mutational enrichment in the constitutively bound CTCF sites with the core motif present (FDR = 7.3 × 10− 43, FC = 1.70), while the signal was clearly attenuated in the constitutively-bound sites with no core motif (FDR = 0.0026, FC = 1.14)." (PMID 33941236, 2021).
oral cancer (1 paper, 2019). "The genome wide transcription factor enrichment profile from ENCODE repository revealed a few prospective TF candidates for regulation of CARM1 expression in oral cancer such as E2F4, CTCF, YY1 and cMyc etc.." (PMID 31217904, 2019).
oral squamous cell carcinoma (1 paper, 2025). "While the transcription factor AP2α has been reported to regulate TCTN1 expression and promote proliferation, migration, and invasion in oral squamous cell carcinoma (OSCC), our study identifies CTCF—rather than AP2α—as a key transcriptional regulator of TCTN1." (PMID 41369411, 2025).
osteoporosis (1 paper, 2023). A condition of reduced bone mass, with decreased cortical thickness and a decrease in the number and size of the trabeculae of cancellous bone (but normal chemical composition), resulting in increased fracture incidence. "The shared presence of CEBPB, CTCF, and TCF12 in the regulatory networks of both BRP and OSP genes suggests their potential involvement in the underlying mechanisms of both bone regeneration and osteoporosis." (PMID 37875547, 2023). "The shared TFs CEBPB, CTCF, and TCF12 in the OSP and BRP genes indicate their potential dual role in bone formation and remodeling, suggesting their involvement in osteoporosis." (PMID 37875547, 2023).
ovarian tumor (1 paper, 2016). "CTCF is an insulator and tumor suppressor gene, whereas BORIS exhibits oncogenetic properties including an anti-apoptotic ability via upregulation of the human Telomerase Reverse Transcriptase (hTERT) gene in embryonic and ovarian tumor cells." (PMID 26849232, 2016).
pilocytic astrocytoma (1 paper, 2015). Pilocytic astrocytoma is a rare subtype of low-grade glioma of the central nervous system characterized by a well circumscribed, often cystic, brain tumor with a discrete mural nodule and long, hair-like projections that extend from the neoplastic astrocytes. "Interestingly, CTCF, a predicted target of miR-542-3p, is down-regulated in pilocytic astrocytoma, and a recent investigation into the higher-order chromatin structure of the INK4/ARF locus in senescent cells, has revealed down-regulation of CTCF in oncogene-induced senescent cells." (PMID 26682910, 2015).
psoriasis (1 paper, 2026). An autoimmune condition characterized by red, well-delineated plaques with silvery scales that are usually on the extensor surfaces and scalp. "Consistent with previous results, high expression levels of CTCF and HSP90AB1 were demonstrated in psoriasis." (PMID 41114929, 2026). "We also noticed that CTCF expression levels in GEO databases (GSE79704 and GSE83582) displayed distinct increase in psoriasis patients." (PMID 41114929, 2026). "Not surprisingly, CTCF displayed higher content in psoriasis patients versus normal controls detected via immunofluorescence." (PMID 41114929, 2026).
renal carcinoma (1 paper, 2020). A carcinoma arising from the epithelium of the renal parenchyma or the renal pelvis. "Previous studies reported that mTOR pathway, GSK3 pathway, AKT pathway, EIF4 pathway, MET pathway, NFAT pathway, and FAS pathway acted as essential factors in the development of renal cancer and that CHREBP2 pathway, EDG1 pathway, and CTCF pathway were also cancer-related pathways." (PMID 33102202, 2020).
reovirus infection (1 paper, 2016). "For example, a gene CTCF was disrupted in a clonal cell lines resisting lytic reovirus infection." (PMID 27632082, 2016).
retinal degeneration (1 paper, 2020). Degeneration of the retina. "Therefore, the potential convergent mechanism for retinal degeneration is transcriptional activation and expression of GDPD1 through juxtaposition of retinal TF binding sites within active compartments bounded by CTCF sites." (PMID 33022222, 2020).
retinoblastoma (1 paper, 2011). A malignant tumor that originates in the nuclear layer of the retina. "Based on the hypothesis that genomic boundaries may contribute to the shielding of CpG-island promoters against silencing, we investigated the contribution of CTCF and DNA methylation to the epigenetic regulation of the human retinoblastoma gene promoter." (PMID 21663659, 2011).
serous carcinoma (1 paper, 2017). "CTCF copy number gain was observed in only a single serous carcinoma sample." (PMID 28319062, 2017).
skin cancer (1 paper, 2017). "However, it has also been reported that in a CTCF haploinsufficient mouse model, CTCF knockdown promoted invasion, metastasis and EMT in lung, liver and skin cancer." (PMID 28977939, 2017).
sterility (1 paper, 2021). "Therefore, the loss of CTCF and BORIS occupancy specifically at CTCF/BORIS sites at the promoters of DEGs is likely the main contributing factor to the sterility of the CM male mice." (PMID 34158481, 2021).
testicular cancer (1 paper, 2025). A primary or metastatic malignant neoplasm that affects the testis. "Furthermore, the mechanisms surrounding CTCF/BORIS could be an essential factor leading to the immortalisation of testicular cancer cells." (PMID 39809819, 2025).